TRIM6 (tripartite motif containing 6)
Diseases named in the same sentence as TRIM6 in open-access papers (continued):
Sharing a sentence is not in itself a finding about the gene and the disease.
renal fibrosis (continued). "With the development of the technologies of drug delivery, different forms of inhibitors targeting TRIM6, i.e., shRNAs and neutralizing antibodies, can be internalized into kidney tissues and cells to suppress TRIM6 expression and treat renal fibrosis in patients with kidney diseases." (PMID 33634104, 2020). "TRIM6 expression was increased in the peripheral blood samples of idiopathic pulmonary fibrosis, but its role in fibrosis-related diseases, i.e., renal fibrosis, still remains veiled." (PMID 33634104, 2020). "Overexpression of TRIM6 increased ubiquitination levels of TSC1 and TSC2 and led to activation of the mTORC1 pathway, thus aggravating renal fibrosis." (PMID 38195664, 2024). "Prior reports have shown that TRIM family proteins play an important role in kidney fibrotic disease, TRIM72, TRIM6 and TRIM18 were involved in the development of renal fibrosis by regulating downstream inflammatory pathways." (PMID 38195664, 2024). "The knockdown of TRIM6 in HK2 cells and 5/6-nephrectomized rats remarkably improved the status of renal fibrosis, which inspires the development of TRIM6 inhibitors for treating renal fibrosis in kidney diseases." (PMID 33634104, 2020). "The expression of TRIM6 promoted the ubiquitination of TSC1 and TSC2, thereby activating mTORC1 and downstream processes of ER stress and EMT in renal fibrosis models." (PMID 33634104, 2020). "As a result, these findings reasonably explain how Ang II induces renal fibrosis in HK2 cells, indicating that TRIM6 is an important but previously unrevealed piece of the puzzle." (PMID 33634104, 2020). "TRIM6 overexpression further led to the activation of downstream processes of EMT and ER stress that contribute to renal fibrosis." (PMID 33634104, 2020). "Clinically, the level of TRIM6, TSC1/2, and NF-κB p50 was found closely related to renal fibrosis." (PMID 33634104, 2020). "The transcription of TRIM6 in HK2 cells followed the same trend with elevated Ang II concentrations, substantiating the correlation between the TRIM6 expression and renal fibrosis." (PMID 33634104, 2020).
breast carcinoma (3 papers, 2022 to 2025). "Comparing to Srsf3 WT liver cancer, Srsf3 KO significantly increases Sox4, E2f1, Trpv4, Trim6, and Myc expression, but does not so in Erbb2 breast cancer." (PMID 40568073, 2025).
gastric cancer (3 papers, 2025). A primary or metastatic malignant neoplasm involving the stomach. "We next explored the mechanism underlying the relatively low level of TRIM6 in the immunological ‘hot’ subtypes of gastric cancer." (PMID 40817248, 2025). "Our results elucidate TRIM6-mediated suppression of antitumor immunity as a novel mechanism underlying ICB resistance in MSS gastric cancer, positioning TRIM6 as both a predictive biomarker and therapeutic target for immunologically cold subtypes." (PMID 40817248, 2025). "Therefore, our data suggested that TRIM6 triggers the proteasomal degradation of cGAS via K27-linked polyubiquitination and negatively regulates cGAS abundance in gastric cancer cells." (PMID 40817248, 2025). "Similarly, TRIM6 expression was found to be positively associated with MLH1 expression in gastric cancer." (PMID 40817248, 2025). "Hypermethylation-mediated TRIM6 downregulation distinguished MSI-H from microsatellite stable (MSS) gastric cancers." (PMID 40817248, 2025). "TRIM6 expression was significantly lower in immunologically ‘hot’ gastric cancers (MSI-H and EBV-positive groups) than in the other two immunologically ‘cold’ subtypes (GS and CIN groups)." (PMID 40817248, 2025). "In summary, our study demonstrates that elevated TRIM6 characterizes MSS gastric cancers and inversely correlates with MSI status." (PMID 40817248, 2025). "Collectively, these data suggest that TRIM6 functions as a critical regulator of ICB resistance in gastric cancer, and genetic ablation of TRIM6 substantially sensitizes gastric tumors to anti-PD-L1 therapy." (PMID 40817248, 2025). "First, we validated the correlation of TRIM6 expression with MSI-H or MSS in different gastric cancer datasets." (PMID 40817248, 2025). "Next, we investigated the immunogenic role of TRIM6 in two different mouse gastric cancer models: the MTC and MFC syngeneic subcutaneous tumor models." (PMID 40817248, 2025). "Trim6 depletion in immunologically ‘cold’ MSS gastric cancer cells promotes CD8+ T-cell infiltration by activating the cGAS-mediated innate immune response and sensitizes these tumors to anti-PD-1/PD-L1 treatment." (PMID 40817248, 2025). "Here, we demonstrated that the RING E3 ligase TRIM6 can degrade cGAS via K27-linked polyubiquitination and impair cGAS-STING signaling in gastric cancer." (PMID 40817248, 2025). "For example, high expression of RECQL4 in HCC or TRIM6 in microsatellite-stable gastric cancer potently suppresses the cGAS-STING pathway, leading to poor T-cell infiltration and likely blunting the response to ablation-driven vaccination without additional targeted modulation." (PMID 41295487, 2025). "In addition, we found that compared with EBV-negative samples, EBV-positive gastric cancer samples presented lower TRIM6 expression." (PMID 40817248, 2025). "Furthermore, gastric cancer patients with low TRIM6 expression were more sensitive to anti-PD-1 therapy, with a better survival outcome." (PMID 40817248, 2025). "Moreover, endogenous co-IP confirmed the interaction between TRIM6 and cGAS in gastric cancer cell lines." (PMID 40817248, 2025). "Collectively, these findings suggest that TRIM6 might contribute to the immunological regulation of gastric cancer by degrading the cGAS protein." (PMID 40817248, 2025). "Through genetic ablation studies in both MSS/MSI-low gastric cancer cell lines and murine MSS models, we show that TRIM6 deletion restores cGAS protein stability, reactivates the cGAS-STING-IFNβ signaling axis, and enhances antitumor immunity." (PMID 40817248, 2025). "Our study reveals that the RING-type E3 ubiquitin ligase TRIM6 correlates with MSI and the immunological status of gastric cancer." (PMID 40817248, 2025). "In the gastric cancer cell lines MKN28 and SNU668, both of which are MSS or MSI-low, we knocked down TRIM6 and found that the cGAS protein level was elevated in shTRIM6 cells, whereas their mRNA expression remained unaffected." (PMID 40817248, 2025).
gastric cancer (continued). "Conversely, TRIM6 depletion in mouse (MTC) and human (MKN28) gastric cancer cells resulted in a significant increase in the mRNA levels of IFNB1 and its downstream genes CXCL10 and ISG15 (or Ccl5) under HT-DNA treatment, and these effects were abolished by simultaneous cGAS knockout." (PMID 40817248, 2025). "To investigate the mechanism by which TRIM6 regulates sensitivity to ICB therapy in gastric cancer, we analyzed tumor-infiltrating lymphocytes via flow cytometry using two mouse tumor models under anti-PD-L1 treatment: MTC (with Trim6 depletion), and MFC (with Trim6 overexpression)." (PMID 40817248, 2025).
myocardial ischemia (2 papers, 2019 to 2023). A disorder of cardiac function caused by insufficient blood flow to the muscle tissue of the heart. "Moreover, TRIM6 has been reported to aggravate myocardial ischemia/reperfusion injury in mice." (PMID 37370144, 2023).
atherosclerosis (1 paper, 2023). A disease characterized by the build-up of fatty material and calcium deposition in the arterial wall resulting in partial or complete occlusion of the arterial lumen. "Experimental manipulation of DNA methylation in engineered human umbilical vein endothelial cells indicated that the identified differentially methylated probes located at TRIM6, TLN2, and FLRT2 genes may play a role in endothelial cell adhesion and atherosclerosis." (PMID 37370144, 2023).
coronary artery disease (1 paper, 2023). "In addition, genetic polymorphisms in the TRIM5/TRIM6 locus have previously been associated with coronary artery disease." (PMID 37370144, 2023).
dermatomyositis (1 paper, 2023). Dermatomyositis (DM) is a type of idiopathic inflammatory myopathy characterized by evocative skin lesions and symmetrical proximal muscle weakness. "Besides tumor correlation, TRIM6 also participates in innate immunity regulation and is reported to be a driver in dermatomyositis." (PMID 38813007, 2023).
gastric tumor (1 paper, 2025). "By using bisulfite sequencing, we found that, compared with that in MSS tumor tissues, TRIM6 promoter methylation was significantly increased in MSI-H gastric tumor samples, which was verified with data from the TCGA-STAD methylation database." (PMID 40817248, 2025). "Genetic ablation of TRIM6 activates innate immunity and sensitizes cold gastric tumors to anti-PD-L1 therapy." (PMID 40817248, 2025). "Our study identifies TRIM6 as a critical negative regulator of the cGAS-STING innate immune pathway in MSS gastric tumors, revealing a potential therapeutic vulnerability." (PMID 40817248, 2025). "TRIM6 ablation enhanced CD8+ T lymphocytes infiltration via cGAS-mediated innate immune response and synergized with anti-PD-L1 therapy in MSS gastric tumors." (PMID 40817248, 2025). "TRIM6 depletion significantly enhances CD8+ T-cell infiltration and sensitizes gastric tumors to anti-PD-1/PD-L1 treatment." (PMID 40817248, 2025).
glioblastoma (1 paper, 2023). The most malignant astrocytic tumor (WHO grade IV). "Further investigation is warranted to comprehensively understand the underlying mechanisms involved in glioblastoma progression and how they intersect with TRIM6 function." (PMID 37759698, 2023). "While high TRIM6 expression has been linked to worse survival outcomes in other tumor types examined in our study, its impact on prognosis appears distinct within the context of Glioblastoma." (PMID 37759698, 2023). "By elucidating such complexities, we can gain valuable insights into potential therapeutic strategies targeting both TRIM6-related pathways as well as other key determinants of glioblastoma prognosis." (PMID 37759698, 2023). "Regarding the relationship between TRIM6 expression and survival outcomes in glioblastoma and WHO Grade 4 patients, our analysis did not reveal a significant correlation." (PMID 37759698, 2023).
idiopathic pulmonary fibrosis (1 paper, 2020). Idiopathic pulmonary fibrosis (IPF) is a nonneoplastic pulmonary disease that is characterized by the formation of scar tissue within the lungs in the absence of any known cause. "Elevated TRIM6 has been observed in the peripheral blood samples of idiopathic pulmonary fibrosis." (PMID 33634104, 2020).
ischemic stroke (1 paper, 2023). A stroke disorder caused by obstruction of blood flow to the brain, due to thrombotic (local blood clot formation) or embolic (due to a blood clot or other material traveling from another site) event. "Altered DNA methylation of the TRIM6, TLN2, and FLRT2 genes may play a functional role in ischemic stroke in Chinese populations." (PMID 37370144, 2023).
lentivirus infection (1 paper, 2019). Virus diseases caused by the Lentivirus genus. "Western blotting analysis showed that compared with vector control (LV-vector), lentivirus infection-mediated TRIM6 overexpression (LV-Trim6) resulted in stark increase in TRIM6 level in the heart." (PMID 31171760, 2019).
liver cancer (1 paper, 2025). An epithelial or non-epithelial malignant neoplasm that arises from the liver. "We further verified the increased expression of Sox4, E2f1, Trpv4, and Trim6 in DEN-induced, Srsf3 KO liver cancer tissues by qRT-PCR." (PMID 40568073, 2025).
lung adenocarcinoma (1 paper, 2023). A carcinoma that arises from the lung and is characterized by the presence of malignant glandular epithelial cells. "A recent study reported a NEAT1-miR-101-3p/335-5p/374a-3p/628-5p-TRIM6 network in lung adenocarcinoma, whose hyper-activation results in upregulated TRIM6 level and poorer prognosis." (PMID 38813007, 2023).
lung carcinoma (1 paper, 2023). "Our findings for the first time define TRIM6 as a negative regulator of ferroptosis in the lung cancer cells, and TRIM6 overexpression enhances the resistance of human lung cancer cells to chemotherapeutic drugs." (PMID 36654781, 2023). "The present study shows the role of TRIM6 on ferroptosis and chemosensitivity of lung cancer, and our major findings are presented as below." (PMID 36654781, 2023). "As expected, TRIM6 silence further decreased the survival and colony formation of the lung cancer cells upon erastin and RSL3 treatment." (PMID 36654781, 2023). "TRIM6 was highly expressed in human lung cancer tissues and cells, and its expression in the lung cancer cells was further increased by ferroptotic stimulation." (PMID 36654781, 2023). "Firstly, TRIM6 is highly expressed in human lung cancer tissues and cells, and its expression in the lung cancer cells is further increased by ferroptotic stimulation." (PMID 36654781, 2023). "Results from IB further confirmed that TRIM6 expression in the lung cancer cells was increased upon ferroptotic stimulation." (PMID 36654781, 2023). "In contrast, TRIM6 silence sensitized human lung cancer cells to cisplatin and paclitaxel in vivo and in vitro." (PMID 36654781, 2023). "Accordingly, Gln uptake was enhanced in the lung cancer cells with TRIM6 silence, but inhibited in those with TRIM6 overexpression." (PMID 36654781, 2023). "Collectively, these data demonstrate a potential involvement of TRIM6 in ferroptosis of the lung cancer cells." (PMID 36654781, 2023). "Overall, our research for the first time defines TRIM6 as a negative regulator of ferroptosis in the lung cancer cells, and TRIM6 overexpression enhances the resistance of human lung cancer cells to chemotherapeutic drugs." (PMID 36654781, 2023). "In summary, our findings determine a novel regulatory role of TRIM6 on ferroptosis and tumor progression of lung cancer." (PMID 36654781, 2023). "Intracellular LIP and Fe2+ levels were increased in the lung cancer cells by ferroptotic stimulation, which were further enhanced in those with TRIM6 silence." (PMID 36654781, 2023). "Herein, we found that human lung cancer tissues and cells exhibited higher TRIM6 expression compared with the ANT or normal lung epithelial cell and that its expression in the lung cancer cells was further increased by ferroptotic stimulation." (PMID 36654781, 2023). "Meanwhile, we found that increased TRIM6 expression in the lung cancer cells upon ferroptotic stimulation could provide cytoprotective effects against chemotherapeutic reagents." (PMID 36654781, 2023). "Genetic or pharmacological inhibition of TRIM6 may provide promising strategies for the treatment of lung cancer." (PMID 36654781, 2023). "In contrast, TRIM6 silence sensitized human lung cancer cells to DDP and PTX in vivo and in vitro." (PMID 36654781, 2023). "Interestingly, TRIM6 overexpression significantly enhanced the survival and colony formation of the lung cancer cells upon ferroptotic stimulation." (PMID 36654781, 2023). "Overall, TRIM6 is a promising therapeutic target for the treatment of lung cancer." (PMID 36654781, 2023). "Given its effective role in regulating ferroptosis, we finally determined whether TRIM6 manipulation affected the chemosensitivity of the lung cancer cells in vivo and in vitro." (PMID 36654781, 2023). "Next, we explored whether TRIM6 expression in the lung cancer cells was altered upon ferroptotic stimulation." (PMID 36654781, 2023). "Lentiviral vectors were used to overexpress or knock down TRIM6 in human lung cancer cells." (PMID 36654781, 2023). "Moreover, TRIM6 knockdown potentiated the lung cancer cells to DDP and PTX treatment in vivo and in vitro." (PMID 36654781, 2023). "We first compared TRIM6 expression in human lung cancer tissues and corresponding ANT." (PMID 36654781, 2023).
lung carcinoma (continued). "Besides, TRIM6 mRNA levels were also increased in serials of the lung cancer cell lines (A549, H358, H460, H1299, PC9, and SPC-A-1) in comparison with the normal human lung epithelial cell BEAS-2B." (PMID 36654781, 2023). "Overall, targeting TRIM6 may help to establish novel strategies to treat lung cancer." (PMID 36654781, 2023). "Secondly, TRIM6 overexpression inhibits, while TRIM6 silence promotes erastin- and RSL3-induced glutaminolysis and ferroptosis in the lung cancer cells." (PMID 36654781, 2023). "Consistent with previous studies, the lung cancer cells with erastin and RSL3 treatment exhibited higher MMP levels that were inhibited by TRIM6 overexpression." (PMID 36654781, 2023). "TRIM6 overexpression inhibited, while TRIM6 silence promoted erastin- and RSL3-induced glutaminolysis and ferroptosis in the lung cancer cells." (PMID 36654781, 2023). "Both TRIM6 and SLC1A5 expressions negatively correlated with patient survival in LUAD database, indicating a clinical role of TRIM6 and SLC1A4 of lung cancer." (PMID 36654781, 2023). "In contrast, TRIM6 silence elevated SLC1A5 expression and ferroptosis of the lung cancer cells." (PMID 36654781, 2023).
melanoma (1 paper, 2025). A malignant, usually aggressive tumor composed of atypical, neoplastic melanocytes. "This inverse correlation between TRIM6 and anti-PD-1 response was further confirmed in highly immunogenic melanoma, supporting TRIM6’s conserved role in immunotherapy regulation." (PMID 40817248, 2025). "Moreover, we also found that TRIM6 depletion inhibited the growth of B16F10 melanoma tumor in syngeneic mice and increased their response to anti-PD-L1 treatment." (PMID 40817248, 2025).
myocardial infarct (1 paper, 2019). "We found that the treatment of both CAY10576 and fludarabine reversed TRIM6-aggravated myocardial infarct size and serum CPK level, therefore illustrating that TRIM6 promotes MI/R injury by inducing IKKε/STAT1 activation-mediated myocardial apoptosis." (PMID 31171760, 2019). "Additionally, TRIM6 depletion reduces and its overexpression increases myocardial infarct size, serum creatine phosphokinase (CPK) level and cardiomyocyte apoptosis in mice subjected to MI/R injury, indicating that TRIM6 functions to aggravate MI/R injury." (PMID 31171760, 2019). "In summary, based on the results we obtained from the MI/R animal model, we propose here that inhibiting TRIM6 expression and/or activity or interfering IKKε-dependent STAT1 activation may present a potential therapeutic option in reducing the size of myocardial infarct and alleviating MI/R injury." (PMID 31171760, 2019).
Parkinson disease (1 paper, 2022). A progressive degenerative disorder of the central nervous system characterized by loss of dopamine producing neurons in the substantia nigra and the presence of Lewy bodies in the substantia nigra and locus coeruleus. "TRIM6 and TRIM24 play an important role in the early stage of Parkinson’s disease and can be used as early warning genes for the development of Parkinson’s disease." (PMID 36249749, 2022).
Stroke (1 paper, 2023). Sudden impairment of blood flow to a part of the brain due to occlusion or rupture of an artery to the brain. "However, findings from our CRISPR/dCas9-Dnmt3a cell model suggest that the observed DNA methylation changes have antagonistic effects suggesting that we identified a mixture of stroke inducing (e.g., TRIM6 gene) as well as neuroprotective (e.g., TLN2 and FLRT2 genes) epigenetic biomarkers." (PMID 37370144, 2023).